MIR505 (microRNA 505)
Synonyms: hsa-mir-505; MIRN505; mir-505
Gene: MicroRNA gene on chromosome X (139,924,148 to 139,924,231, reverse strand). Ensembl gene ENSG00000207633.
Gene Ontology:
Biological process: miRNA-mediated post-transcriptional gene silencing
Cellular component: RISC complex
Homologues: Orthologues: chimpanzee ptr-mir-505 (100% identical), macaque mml-mir-505 (100% identical), guinea pig MIR505 (99% identical), mouse Mir505 (96% identical), pig ssc-mir-505 (93% identical), dog MIR505 (90% identical), rabbit MIR505 (73% identical).
Diseases named in the same sentence as MIR505 in open-access papers:
MIR505 is named in the same sentence as 1 disease in open-access papers, as found by Europe PMC text mining. Sharing a sentence is not in itself a finding about the gene and the disease.
MIR505 shares sentences with these, for which no sentence is quoted: spina bifida (1 paper).